IDO1 (indoleamine 2,3-dioxygenase 1)
Diseases named in the same sentence as IDO1 in open-access papers (continued):
Sharing a sentence is not in itself a finding about the gene and the disease.
cervical carcinoma (continued). "IDO1 is a potential target for immunotherapy for cervical cancer." (PMID 39312339, 2024). "Here, we explored the prognostic significance of IDO1 in cervical carcinoma." (PMID 39312339, 2024). "Consequently, we ascertained that IDO1 expression most significantly influences the one-year survival rate and prognosis in cervical cancer patients." (PMID 39312339, 2024). "IDO1 is a rate-limiting enzyme in the extracellular tryptophan catabolism pathway via kynurenine, and it has been proven to be abnormally highly expressed in malignant tumors such as cervical cancer and esophageal cancer." (PMID 38443340, 2024). "Overall, IDO1 holds potential as a therapeutic target for cervical cancer." (PMID 39312339, 2024). "IDO-1 expression was primarily observed in cellular infiltration within cervical cancer samples." (PMID 37626777, 2023). "The overexpression of miR-218 considerably suppressed the expression of IDO1, inhibited cell viability, and promoted the caspase-mediated cell death of cervical cancer cells through the transfection of miR-218 mimics into HeLa cervical cancer cells." (PMID 35464451, 2022). "IDO1 expression could be detected in cervical cancer tissues and was higher than that of the normal cervical epithelium." (PMID 33390854, 2021). "Additionally, combining the IDO1 inhibitor with nivolumab is safe and improves response rates in bladder and cervical cancer patients." (PMID 34101386, 2021). "IDO1 was highly detected in cervical cancer tissue and low expression in normal tissue." (PMID 34778035, 2021). "The present study also provides support for the application of IDO1 inhibitors in cervical cancer." (PMID 34778035, 2021). "Collectively, the data indicated that IFN-γ could promote IDO1 expression in cervical cancer cells and induce its activity, which resulted in the conversion of tryptophan to kynurenine." (PMID 33390854, 2021). "The suppressive effect to the proliferation of Jurkat T cells with the conditional media collected from irradiated HeLa and SiHa cells was significantly enhanced in comparison to non-irradiated cells, supporting the observations of the IDO1 upregulation in irradiated cervical cancer cells." (PMID 32545442, 2020). "We further discovered that the reduction of IDO1 expression also inhibited Notch1 activation and the addition of kynurenine, the first breakdown product of IDO1 mediated tryptophan metabolism, increased the self-renewal capability of cervical cancer cells." (PMID 32545442, 2020). "Our data provide a reciprocal regulation mechanism between IDO1 and Notch1 expression in cervical cancer cells and suggest that the IDO1 inhibitors may potentially be used as radiosensitizers." (PMID 32545442, 2020). "RT-qPCR was used to detect the expression levels of miR-218 and IDO1 in 37 cervical cancer tissues." (PMID 30314496, 2018). "MiR-218 inhibits immune escape of cervical cancer cells by direct downregulating IDO1." (PMID 30314496, 2018). "Therefore, we studied the expression of miR-218 and IDO1 in some commonly used cervical cancer cells (HeLa, SiHa, C-33, and Caski cells), and the results showed the miR-218 was inhibited and the IDO1 levels were promoted." (PMID 30314496, 2018). "The expression of miR-218 was negatively correlated with IDO1 in cervical cancer tissues and cells." (PMID 30314496, 2018). "The expression of miR-218 was negatively correlated with IDO1 in cervical cancer." (PMID 30314496, 2018). "RT-qPCR and Western blot were performed to detect the expression of IDO1 in cervical cancer." (PMID 30314496, 2018). "Importantly, the immunosuppressive enzyme IDO1 showed a significantly higher mRNA expression level in cervical cancer than in normal cervix, and also in comparison to other cancers." (PMID 28670312, 2017).
cervical carcinoma (continued). "Due to the observations that the inhibition of IDO1 activity enhanced the radiosensitivity of cervical CSCs, we hypothesize that the IDO1 inhibitors could function as radiosensitizers for helping the radiation therapy in cervical cancer." (PMID 32545442, 2020). "Thus, miR-218 might have critical regulatory functions on the molecular mechanism of IDO1 in cervical cancer." (PMID 30314496, 2018). "IDO1 overexpression and IFN-γ treatment increased Kyn accumulation and reduced tryptophan to induce autophagy more powerfully in cervical cancer cells." (PMID 38539263, 2024). "A statistically significant positive correlation was also observed between the transcript levels of IDO1 and IFN-γ in 144 cervical cancer samples." (PMID 38540186, 2024). "In conclusion, the combined inhibition of IDO-1 and CXCR-2 is helpful in the antitumor response against preclinical cervical cancer." (PMID 37626777, 2023). "To investigate the mRNA expression of the IDO1 and CXCL genes of human cervical cancer, we performed an analysis based on the cancer genome atlas (TCGA) and genotype tissue expression (GTEx) data using the GEPIA2 platform." (PMID 37626777, 2023). "Our results revealed that the simultaneous inhibition of IDO-1 and CXCR-2 induced antitumor effects in cervical cancer." (PMID 37626777, 2023). "In cervical cancer, existing studies have shown that IFN-γ activated autophagy of cervical cancer cells and macrophage phagocytosis reactivation through IDO1 overexpression and kynurenine metabolism." (PMID 34717710, 2021). "This suggests that IDO1 is a tumor immunity and tumor escape related gene in CESC and can be used as a new target for cervical cancer therapy." (PMID 34778035, 2021). "As indoleamine-2,3-dioxygenase 1 (IDO1) is critical in tumor immune escape, we determined to study the regulatory mechanism of miR-218 on IDO1 in cervical cancer." (PMID 30314496, 2018). "Furthermore, IDO-1 has been reported to be involved in the self-renewal and expression of OCT4 and SOX2 in cervical cancer stem cells." (PMID 37626777, 2023). "In the same study, Kyn/Trp ratio in cervical cancer tissue was correlated with IDO1 mRNA expression and not with IDO2 indicating that the increased IDO activity is due to IDO1 activity rather than IDO2." (PMID 36039641, 2022). "Additionally, a clinical phase I/II with an IDO inhibitor (BMS-986205) in combination with nivolumab showed promising results, with response rates of 46% in bladder cancer and 25% in cervical cancer (Blocking IDO1 Helps Shrink Bladder, Cervical Tumors, 2018)." (PMID 36263134, 2022). "In addition, high-level IDO1 and low-level miR-218 were correlated to advanced FIGO stages and low differentiated histological features of cervical cancers, as well as low survival rates in 2 years." (PMID 30314496, 2018). "We therefore mapped the immunohistochemical distribution of the IDO1 and IDO2 proteins at the human maternal–fetal interface using a rare early pregnancy sample from a women at seven weeks of gestation who underwent hysterectomy for cervical cancer with gestational sac in utero." (PMID 38674162, 2024). "The IDO1 inhibitor is not an ideal treatment for cervical cancer, whereas immunotherapy is still a significant treatment strategy used to improve the outcome of advanced cervical cancer patients." (PMID 33390854, 2021). "This may partly explain why IDO1 inhibition could not increase the number of cervical cancer patients who achieved satisfactory treatment response." (PMID 33390854, 2021). "The protein expression of IDO1 and CD8+ T cells markers in cervical cancer tissues and normal cervical tissues was verified using the HPA online database." (PMID 34778035, 2021). "The clinical pathological features were determined, and our results indicated that high IDO1 levels were correlated to advanced FIGO stages and low differentiated histological features of cervical cancer; however, it was not correlated with ages." (PMID 30314496, 2018).
atherosclerosis (45 papers, 2017 to 2025). A disease characterized by the build-up of fatty material and calcium deposition in the arterial wall resulting in partial or complete occlusion of the arterial lumen. "Conversely, the inhibition of IDO1 using 1-MT inhibited the development of atherogenesis in high-fat diet-fed, atherosclerosis-prone apolipoprotein E-deficient mice." (PMID 39120289, 2024). "Using Apoe−/− and Apoe−/−Ido1−/− mice that were fed a high-fat, high-cholesterol diet (HFCD) to simultaneously induce NASH and atherosclerosis, we found that Ido1 deficiency significantly accelerated atherosclerosis after 7 weeks." (PMID 35563591, 2022). "Consistent with previous animal experiments suggesting IDO is protective against atherosclerosis, this MR study showed that plasma IDO1 protein was inversely associated with IHD." (PMID 31186442, 2019). "Specifically, IDO1 activity displayed a significant association with a range of atherosclerosis risk factors for the female population, including age, LDL cholesterol (LDL-C), and BMI." (PMID 28377795, 2017). "Additionally, recent evidence supports the key role for the KP in the regulation of inflammation and tolerance mechanism linked to atherosclerosis, thus IDO1 emerges as a key atheroprotective enzyme promoting immune homeostasis." (PMID 35211110, 2021). "The study also demonstrated that hsa_circ_0004104 may contribute to the pathogenesis of CAD by upregulating of atherosclerosis-susceptible genes, such as IDO1, MMP8, CD40, and downregulating of anti-atherosclerosis genes, such as ApoA I, RNASE1." (PMID 33421993, 2021). "However, in most animal experiments, inhibition of IDO or IDO deficiency in mice leads to early atherosclerosis and plaque instability, although one study showed an inverse association of IDO1 deficiency with the risk of atherosclerosis." (PMID 31186442, 2019). "Inflammation in the preliminary stages of atherosclerosis has a significant impact on IDO1, and IDO1 and the IDO1-associated pathway constitute critical mediating agents associated with the immunoinflammatory responses that characterize advanced atherosclerosis." (PMID 28377795, 2017). "Considering that changes in IDO1 may also be influenced by the stages of atherosclerotic disease and that IDO1 and the disease may be mutually causative, investigating IDO1-related drug mechanisms at various stages of atherosclerosis is imperative." (PMID 38883986, 2024). "Also, the overactivation of the IDO1 axis has been associated with reduced inflammation and atherosclerotic burden in hyperlipidemic mice, whereas inhibition of IDO1 activity has been linked with increased vascular inflammation and acceleration of atherosclerosis in Apoe–/– mice." (PMID 37081894, 2023). "A study showed that indoleamine 2,3-dioxygenase 1 (IDO1) promotes atherosclerosis by inhibiting IL-10 production, which activates a cAMP-dependent pathway and suppresses Erk1/2 phosphorylation, leading to increased plaque instability." (PMID 40356907, 2025). "During atherosclerosis regression, macrophage IDO1 knockdown obstructs responses that contribute to plaque-stabilizing characteristics." (PMID 41000074, 2025). "During atherosclerosis regression, IDO1 knockdown in macrophages obstructs plaque stabilization responses." (PMID 41000074, 2025).
atherosclerosis (continued). "Despite lingering uncertainties, multiple studies have demonstrated that the application of IDO1 inhibitors can delay the progression of atherosclerosis, affirming that inhibiting IDO1 can indeed serve as a novel therapeutic target for cardiovascular diseases." (PMID 38883986, 2024). "Despite the well-established protective effect of IDO1 against established atherogenesis, it also exhibits pro-atherosclerotic functions during the developmental stages of atherosclerosis." (PMID 39120289, 2024). "While IDO1 exhibits a protective role against atherosclerosis in its early stages, it also promotes the progression of atherosclerosis in later stages." (PMID 38883986, 2024). "Modulating IDO1 can effectively delay the progression of atherosclerosis and reduce systemic inflammation." (PMID 38883986, 2024). "In line with our previous studies, ablation of IDO activity (Apoe−/−Ido1−/−) significantly increased atherosclerosis in the aortic arch compared to Apoe−/− mice." (PMID 35563591, 2022). "IDO1 ablation is usually followed by increased inflammation in different disease models, including atherosclerosis." (PMID 35563591, 2022). "IDO-1, which is an enzyme that catalyzes the oxidation of the indole moiety, plays a crucial role in obesity, atherosclerosis, vascular inflammation, and aneurysm by regulating the development and maintenance of the immune system." (PMID 35719088, 2022). "Mechanistically, IDO1 activity in macrophages drives atherosclerosis and increased plaque size by generating kynurenine which, in turn, inhibits the production of the anti-inflammatory cytokine IL-10." (PMID 36144238, 2022). "Genetic and pharmacological inhibition of IDO-1 led to substantial increase in vascular inflammation and atherosclerosis in Apoe−/− mice." (PMID 35348183, 2022). "IDO1 has been suggested to play a protective role in atherosclerosis due to its potential immunomodulatory effect." (PMID 34630411, 2021). "Regulatory T cells participate in atherosclerosis by promoting plaque stabilization and influence inflammation by inducing IDO-1 expression in antigen-presenting cells." (PMID 33117340, 2020). "Another suggested mechanism by which IDO-1 protects against atherosclerosis is through inhibition of IL-10 production by a kynurenic acid (KA)-induced mechanism." (PMID 33117340, 2020). "In the present study, we revealed the proatherosclerotic function of IDO1 in the developmental stages of atherosclerosis." (PMID 31637003, 2019). "A previous study has shown that inhibition of IDO1 can increase atherosclerosis in ApoE−/− mice, which raises concerns for the potential pharmaceutical application of IDO1 inhibitors." (PMID 31637003, 2019). "Our study indicated that IDO1 played a complicated and unfixed role in the entire process of atherogenesis, despite the atheroprotective role in established atherosclerosis." (PMID 31637003, 2019). "Given the involvement of IDO1 in established atherosclerosis, we attempted to clarify the role of IDO1 in the developmental process of atherosclerosis." (PMID 31637003, 2019). "Given that the expression and activity of IDO1 varied with the different grades of the histological classification of atherosclerosis, we sought to clarify the involvement of IDO1 in established atherogenesis." (PMID 31637003, 2019). "Compared to the protective effect of IDO1 against established atherogenesis, the role of IDO1 in the developmental process of atherosclerosis is still unclear." (PMID 31637003, 2019).
atherosclerosis (continued). "The discrepancy of indoleamine 2, 3-dioxygenase 1 (IDO1) function in atherosclerosis has been noted." (PMID 31637003, 2019). "We concluded that IDO1 played a proatherosclerotic role in the developmental process of atherosclerosis." (PMID 31637003, 2019). "Altogether, our data suggest that Tregs and IDO1-mediated Trp metabolism can mutually regulate one another in the vessel wall to promote vascular tolerance mechanisms that limit inflammation and atherosclerosis." (PMID 29867939, 2018). "In line with this, recent studies suggest that IDO-1 expression have a detrimental role in aneurysm, atherosclerosis and obesity." (PMID 30619249, 2018). "Interestingly, in dendritic cells, IDO1 displayed a mitigating effect on atherosclerosis by fostering the proliferation and differentiation of Tregs in vitro through the KYN-AhR." (PMID 38883986, 2024). "Therefore, the precise regulation of IDO1 levels throughout the stages of atherosclerosis holds significant clinical significance in cardiovascular disease." (PMID 38883986, 2024). "Furthermore, the application of the IDO1 inhibitor 1-MT has been shown to increase vascular inflammation, exacerbating atherosclerosis." (PMID 38883986, 2024). "Furthermore, mice with atherosclerosis exhibit markedly elevated levels of IDO1 compared to wild-type mice, and serum IDO1 levels are positively correlated with the advanced stages of atherosclerosis." (PMID 38883986, 2024). "Additionally, the role of IDO1 in atherosclerosis is currently uncertain, with some evidence suggesting a protective function of IDO1 in modulating atherosclerosis and inflammation." (PMID 38883986, 2024). "Alteration in TRP catabolites was monitored in atherosclerosis and an elevated expression of indoleamine-2,3-dioxygenase (IDO)-1/2, the first and rate-limiting enzyme catabolizing both D and L-tryptophan to KYN was observed in the macrophage-rich cores of human advanced atherosclerotic plaques." (PMID 37616231, 2023). "In conclusion, we show that Ido1 deficiency aggravates atherosclerosis, but not liver disease, in a newly established NASH and atherosclerosis comorbidity model." (PMID 35563591, 2022). "Indoleamine 2,3-dioxygenase-1 (IDO1), the rate-limiting enzyme of the kynurenine pathway of tryptophan (Trp) metabolism, has been identified as a key immunomodulatory enzyme implicated in different diseases, including atherosclerosis and liver disease." (PMID 35563591, 2022). "As macrophages are crucially involved in vascular inflammation and the pathogenesis of atherosclerosis, changes in IDO1 activity might play a role in these diseases as well." (PMID 35451695, 2022). "As we have previously shown using pharmacological and genetic approaches, IDO1 ablation increases vascular inflammation and accelerates atherosclerosis, which could now be reproduced using a HFCD." (PMID 35563591, 2022). "It has been proposed that IDO-1 expression affects atherosclerosis via multiple mechanisms." (PMID 35348183, 2022). "In vascular inflammation and atherosclerosis, IDO1 activity in bone marrow-derived macrophages was proposed to have adverse effects by inhibition of the anti-inflammatory cytokine IL-10 via kynurenic acid mediated activation of a cAMP-dependent pathway and inhibition of Erk1/2 phosphorylation." (PMID 35451695, 2022). "IDO1 is expressed in human atherosclerosis where it co-localizes with macrophages." (PMID 34630411, 2021). "Moreover, elevated IDO-1 is correlated with a reduction of human and mouse atherosclerosis, where plasmacytoid dendritic cells (pDCs) overexpress IDO-1 and modulate T cell responses." (PMID 33117340, 2020). "Also, inhibition of IDO-1 in ApoE−/− mice has been shown to lead to increased vascular inflammation and atherosclerosis." (PMID 33117340, 2020).